FTO (FTO alpha-ketoglutarate dependent dioxygenase)
Diseases named in the same sentence as FTO in open-access papers (continued):
Sharing a sentence is not in itself a finding about the gene and the disease.
bladder cancer (continued). "Moreover, we found that FTO silencing in bladder cancer cells could significantly (p < 0.001) upregulate, by 1.5‐fold, the relative m6A level of MALAT1 5′‐End, whereas the overexpression of FTO could significantly (p < 0.001) decrease, by 24.3%, the relative m6A level of MALAT1 5′‐End." (PMID 33634966, 2021). "Posttranslational modifications, including the elevation of FTO protein levels in bladder cancer via USP18 deubiquitination, may also serve a pivotal function in the pathophysiological processes mediated by FTO." (PMID 39449798, 2024). "Similarly, FTO-mediated m6A removal in MALAT1 mRNAs activated the MALAT1/miR-384/MAL2 cascade, leading to the development of bladder cancer." (PMID 38556586, 2024). "It was found in humans and animal models that METTL3, FTO, IGF2BP1, IGF2BP3, YTHDF1, YTHDF 2, ELAV-like protein 1 (ELAVL1), HNRNPA2B1 were upregulated in bladder cancer cells." (PMID 37701836, 2023). "FTO, IGF2BP3, and YTHDC1 have a significant difference in bladder cancer and prognosis." (PMID 35251177, 2022). "The higher amounts of FTO protein but not mRNA was also detected in a panel of bladder cancer cell lines in comparison to normal uroepithelial SV-HUC-1 cells." (PMID 33461172, 2021). "We also used the immunohistochemical results of Human Protein Atlas database to explore the expression of independent prognostic factor in bladder cancer and found that YTHDC1 and FTO levels in normal bladder tissues were significantly higher than in bladder cancer tissues." (PMID 34521394, 2021). "In addition, a significant correlation was found between MAL2 expression and the smoking status (p = 0.0192) and pathologic stage (p = 0.0104) of the bladder cancer patients in cohort 2 and between MAL2 expression and FTO expression." (PMID 33634966, 2021). "In this study, we demonstrated that the post-translational deubiquitination by USP18 up-regulates the protein but not mRNA of FTO in bladder cancer tissues and cells." (PMID 33461172, 2021). "Consistently, we found that the cisplatin-induced cytotoxicity of bladder cancer cell could be rescued by co-treatment with MA2, which was previously reported as a highly selective inhibitor of FTO, compared with the cisplatin-control group." (PMID 32299393, 2020). "Consistently, the cisplatin-induced cytotoxicity of bladder cancer cell could be rescued by co-treatment with MA2, which was a highly selective inhibitor of FTO." (PMID 32299393, 2020). "In the present study, we found that the cisplatin-induced cytotoxicity of bladder cancer cells could be rescued by co-treatment with MA2, which was a highly selective inhibitor of FTO." (PMID 32299393, 2020). "The enrichment of FTO-related gene pathways indicated that FTO might be involved in the regulation of focal adhesion/Hippo signaling pathway/TGF-β signaling, these results suggest that FTO plays an important role in bladder cancer." (PMID 35311150, 2022). "In addition, in our cell cycle analysis, the cell cycle was arrested in the G0/G1 stage after FTO knockdown, which might be explained by the corresponding decreased expression of CDK6 in bladder cancer cells." (PMID 34725345, 2021). "Moreover, we also analysed FTO expression in T24, 5637, UM-UC-3, SW 780, 253 J and SV-HUC cell lines and found that the mRNA and protein levels of FTO were significantly higher in bladder cancer cell lines than in the normal urinary epithelial cell line SV-HUC." (PMID 34725345, 2021). "Overall, in bladder cancer cells, knockdown of FTO significantly (p < 0.001) decreased the relative expression level and half‐life of MALAT1 mRNA, whereas FTO overexpression significantly increased, by 2.2‐fold, the relative expression level and half‐life of MALAT1 mRNA." (PMID 33634966, 2021). "For the limitation of sample size, stageI was excluded for analysis of YTHDC1, FTO and WTAP mRNA expression between bladder cancer and the normal controls." (PMID 34521394, 2021).
bladder cancer (continued). "Specifically, only the FTO gene, and not the ALKBH5 gene, was highly overexpressed in the tissue of bladder cancer." (PMID 33634966, 2021).
heart failure (39 papers, 2013 to 2026). Inability of the heart to pump blood at an adequate rate to meet tissue metabolic requirements. "In this study, we discover the harmful signaling pathways that are triggered by m6A imbalance and FTO loss, which eventually lead to adverse cardiac remodeling and heart failure." (PMID 41327199, 2025). "Conversely, knockdown of FTO in cardiomyocytes substantially increases arrhythmia susceptibility, suggesting that FTO is essential in the onset and progression of heart failure." (PMID 41007727, 2025). "Although FTO-mediated m6A modification has been linked to cardiac remodeling and heart failure in previous studies, the novelty of our work lies in dissecting the early phase of pressure overload–induced remodeling." (PMID 41327199, 2025). "m6A-RNA-methylation is regulated by the demethylase, fat mass and obesity-associated protein (FTO), and FTO protein levels are diminished in heart failure." (PMID 41327199, 2025). "Elevation of m6A level by overexpression of the m6A writer METTL3 can cause cardiac hypertrophy, while m6A eraser FTO attenuates cardiac dysfunction in mice with pressure overload-induced heart failure via N6-demethylation." (PMID 38172650, 2024). "The association between FTO-mediated m6A demethylation and cardiovascular disease, including heart failure, has also drawn the attention of researchers." (PMID 35628623, 2022). "Mathiyalaganet al. showed that the expression of FTO is downregulated in the cardiomyocytes of mice with heart failure, which causes abnormally increased levels of m6A methylation in the heart and SERCA2a." (PMID 35406663, 2022). "We detected a novel association between the BMI-increasing allele of the FTO variant and increased odds/hazard ratios of ever and incident heart failure." (PMID 23824655, 2013). "Loss of FTO leads to rapid progression into severe heart failure, shifting cardiomyocyte remodeling from hypertrophy toward atrophy and apoptosis, driven by mTORC1–S6K1 hyperactivation and impaired autophagy, while pharmacological inhibition of mTORC1–S6K1 rescues the pathology." (PMID 41327199, 2025). "Moreover, decreased expressions of fat mass and obesity-associated protein (FTO) have been related to heart failure, and overexpression of FTO in failing heart results in decrease of ischemia-triggered loss of cardiac function." (PMID 35211628, 2022). "FTO, a demethylase, plays an important role in DNA and RNA methylation and has been implicated in cardiac defects, including hypertrophic cardiomyopathy, arrhythmias, coronary heart disease and heart failure." (PMID 34310344, 2021). "This novel functional regulations of FTO add a new dimension of therapeutic interventions for the treatment of cardiac hypertrophy and heart failure at the early phase." (PMID 41327199, 2025). "In the context of m6A RNA methylation, heart failure is characterized by marked increase in global m6A methylation and steady downregulation in FTO expression in both rodents and human failing hearts." (PMID 41327199, 2025). "In a recent study, a team created a model of transverse aortic constriction-induced heart failure (HF) in mice and found that cardiac fibrosis and hypertrophy were ameliorated in mice overexpressing FTO." (PMID 40005339, 2025). "FTO downregulation in these patients drives maladaptive signaling by these episodes eventually explaining the decompensation-triggered progression of heart failure." (PMID 41327199, 2025). "Research on FTO’s roles in cardiovascular diseases, particularly in myocardial fibrosis, heart failure, atherosclerosis, and myocardial ischemia, has gained momentum, revealing its various biological effects in the pathophysiology conditions." (PMID 39869517, 2025). "Regulation of FTO levels was observed in MI and heart failure (HF) patients and corresponding animal models." (PMID 39744011, 2024).
heart failure (continued). "FTO is critically involved in the initiation and progression of cardiovascular diseases, including myocardial fibrosis, heart failure, and atherosclerosis." (PMID 39192357, 2024). "In contrast to these data, the negative role of FTO has been documented in mice with HFpEF (heart failure with preserved ejection fraction), where upregulated FTO levels were reduced by exercise training." (PMID 39744011, 2024). "Another study showed that the m6A demethylase FTO attenuated cardiomyocyte contractile dysfunction by regulating glucose uptake and glycolysis in mice with pressure overload-induced heart failure." (PMID 37238719, 2023). "This review focused on the functional role and molecular mechanisms of FTO in CVDs, including myocardial fibrosis, heart failure, and atherosclerosis, providing a new direction for further research on the pathogenesis and treatment of CVDs." (PMID 37238719, 2023). "An increasing number of studies have indicated that FTO can mediate the m6A demethylation of target mRNAs to affect the initiation and progression of CVDs, such as myocardial fibrosis, heart failure, atherosclerosis, and aortic aneurysm." (PMID 37238719, 2023). "Consistent with this, a recent study reported that FTO downregulation reduced the contraction of hypoxic cardiomyocytes, resulting in heart failure." (PMID 37238719, 2023). "Recent studies have shown that FTO effectively enhances the contractile function of cardiomyocytes, thereby regulating heart failure." (PMID 37238719, 2023). "In the heart, m6A demethylase FTO has been shown to be downregulated in heart failure patients and mouse hearts." (PMID 36351918, 2022). "Restoring FTO expression in heart failure attenuated the ischemia-induced increase in m6A and rescued cardiac contractile function." (PMID 35461308, 2022). "In the process of heart failure, the expression of m6A demethylase FTO in cardiomyocytes decreases, the expression of writing proteins such as METTL4/14 increases, and the content of m6A in failed heart and hypoxic cardiomyocytes increases." (PMID 35811741, 2022). "In comparison, studies have reported that m6A methylation and FTO have decreased expressions in various pathologic conditions including heart failure and endotoxemia- and hypoxia-/reoxygenation-induced cardiac cell injuries." (PMID 35402566, 2022). "The target transcriptions of METTL3 or FTO determine their roles of in the progression of heart failure." (PMID 35836571, 2022). "It has previously been documented that compared with normal heart tissue, the level of m6A modification is higher and FTO expression level is lower in myocardium tissue of mice with ischemic damage and heart failure." (PMID 35858921, 2022). "FTO expression in the hearts of heart failure patients was significantly lower than that in the hearts of control individuals." (PMID 35461308, 2022). "The FTO intervenes the pathogenesis of heart failure through m6A, which provides a new perspective for elucidating the pathogenesis of heart failure." (PMID 34489709, 2021). "Two different groups have demonstrated that FTO was downregulated in mice failing hearts due to MI, and the overexpression of FTO exerted striking cardioprotection against heart failure by demethylating specific m6A methylated targets." (PMID 35004673, 2021). "In the heart, m6A demethylase FTO has been shown to be decreased in heart failure patients and animal hearts, and upregulation of FTO could decrease fibrosis and enhance angiogenesis, thereby attenuating cardiac dysfunction after ischemia injury." (PMID 41509912, 2026). "Interestingly, previous studies have demonstrated a key regulatory role of FTO-dependent m6A methylation in the development of heart failure." (PMID 41509912, 2026). "Furthermore, previous studies have suggested that FTO overexpression can inhibit myocyte apoptosis and enhances myocyte contractile function, resulting in the improvement of heart failure." (PMID 41509912, 2026).
heart failure (continued). "Thus, FTO modulates Eci1 expression through m6A-dependent mechanisms, facilitates fatty acid metabolism and mitigates pressure overload-induced heart failure during exercise." (PMID 41594638, 2026). "Also, we uncovered the detrimental pathways of pathological remodeling in relation to the imbalance in the FTO-m6A pathway and its role in heart failure." (PMID 41327199, 2025). "Enhancing FTO expression in heart failure mouse reduced the ischemia-triggered rise in m6A levels and the decline in cardiac contractile function, which selectively demethylates cardiac contractile mRNAs, preventing the degradation and enhancing protein expression during ischemia." (PMID 39869517, 2025). "Additionally, FTO mitigates heart dysfunction in pressure-overloaded heart failure mice by regulating glucose uptake and glycolysis." (PMID 39192357, 2024). "Specifically, FTO overexpression suppressed myocardial cell apoptosis induced by hypoxia/reoxygenation by modulating the m6A modification of Mhrt, thereby ameliorating heart failure." (PMID 39192357, 2024). "Furthermore, reduced FTO expression in heart failure leads to abnormal increases in cardiac m6A levels and m6A in selective contractile transcripts." (PMID 39192357, 2024). "METTL3 and FTO were proved to be the key regulators of m6A methylation in failure heart." (PMID 35836571, 2022). "These suggest FTO is a potential therapeutic in the treatment of heart failure." (PMID 35836571, 2022). "Additionally, the time from left ventricular hypertrophy to heart failure is significantly shortened in FTO-knockout mice." (PMID 35406663, 2022). "This may be explained by the fact that METTL3 and FTO participate in the progression of heart failure by regulating m6A methylation of target transcriptions rather regulating than the global level of m6A methylation." (PMID 35836571, 2022). "Increased FTO in the heart failure model mice reduces the ischemia-induced m6A and improves the cardiac contractile function, which may be related to the selective demethylation of cardiac contractile transcripts by FTO." (PMID 34489709, 2021). "Additionally, FTO plays a regulatory role in improving glucose levels and may have implications in protecting the injured heart or improving heart function in heart failure patients." (PMID 40005339, 2025). "Hence, the methylation deregulation-induced pathological turnover might be the basis for the impaired compensatory hypertrophy and maldaptive remodeling in FTO depleted hearts, eventually resulting in cardiac insufficiency and heart failure." (PMID 41327199, 2025). "Similarly, mice with heart failure (HFpEF) exhibited decreased FTO levels in the heart after physical training while overexpression of FTO abolished the health benefits of exercise in these mice by promoting myocyte apoptosis, myocardial fibrosis, and myocyte hypertrophy." (PMID 37331009, 2023). "More recently, a study revealed that FTO could alleviate cardiac dysfunction in mice with pressure overload-induced heart failure by regulating glucose uptake and glycolysis through facilitating the expression of glycolysis-related genes such as phosphoglycerate mutase 2 (PGAM2)." (PMID 35628623, 2022). "However, the expression level of m6A demethylase FTO is low in cardiac fibrosis induced by MI, hypoxia, and heart failure, and overexpression of FTO inhibits the activation, proliferation, and migration of cardiac fibroblasts and alleviates the development of cardiac fibrosis." (PMID 35954191, 2022). "In addition, FTO knockout can lead to impaired cardiac function and promote heart failure." (PMID 34368154, 2021). "Studies have confirmed that FTO and ALKBH5 play a significant role in the development of embryo heart and cardiovascular disease, such as atherosclerosis, coronary heart disease (CHD) and heart failure." (PMID 35836571, 2022).
heart failure (continued). "A recent study demonstrated that FTO regulates glycolysis in an m6A-dependent manner and also regulated glucose metabolism by modulating the Akt-GLUT4 axis in the heart failure mouse model, thus regulating the energy supply in the cardiac function and structure." (PMID 36157472, 2022). "In addition, FTO significantly reduced fibrosis and scar area in AMI mouse models, which were critical for preventing heart failure after AMI." (PMID 36440046, 2022). "Therefore, in the future, the research on FTO and METTL3 related myocardial ischemia and hypoxia may find a breakthrough for the therapeutic target of heart failure." (PMID 35811741, 2022).